OVCH1 (ovochymase 1)
Synonyms: OVCH
Tractability: Antibody: UniProt places it where antibodies can reach, with medium confidence; UniProt predicts a signal peptide or a membrane-spanning region; its Gene Ontology location is reachable by antibodies, with medium confidence.
Gene: Protein-coding gene on chromosome 12 (29,412,474 to 29,497,686, reverse strand). Ensembl gene ENSG00000187950.
Subcellular location: Secreted
Gene Ontology:
Molecular function: serine-type endopeptidase activity
Biological process: fertilization; proteolysis
Cellular component: extracellular region
Genetic constraint (gnomAD): Loss-of-function variants: 112 observed, 112.12 expected, observed/expected ratio (o/e) 1, 90% interval 0.86 to 1.17. The upper end of that interval is the gene's LOEUF score, 1.17, which puts it in group 5 of 6, group 1 being the genes least tolerant of losing a copy. Missense variants: 1,216 observed, 1,225.6 expected, observed/expected ratio (o/e) 0.99, 90% interval 0.95 to 1.04. Synonymous variants: 417 observed, 425.45 expected, observed/expected ratio (o/e) 0.98, 90% interval 0.9 to 1.06.
Homologues: Orthologues: chimpanzee OVCH1 (94% identical), macaque OVCH1 (86% identical). Paralogues in human: PRSS48 (9% identical), PLAT (9% identical), PLG (9% identical), TMPRSS12 (9% identical), PRSS33 (8% identical), PRSS50 (8% identical), KLK9 (8% identical), PRSS27 (8% identical), KLK15 (8% identical), PRSS57 (7% identical), GZMM (6% identical), PRSS37 (5% identical), and 2 more.